CD34 (CD34 molecule)
Diseases named in the same sentence as CD34 in open-access papers (continued):
Sharing a sentence is not in itself a finding about the gene and the disease.
mesenchymal tumors (48 papers, 2011 to 2026). "NTRK fusion-associated mesenchymal neoplasm exhibits simultaneous expression of S100 and CD34, as well as the presence of NTRK gene fusion identified using FISH or NGS testing." (PMID 39410565, 2024). "Indeed, coexpression of S100 (usually variable and patchy) and CD34 represents a valuable clue to tyrosine kinase fusion associated mesenchymal neoplasms originating at different anatomic sites." (PMID 39196362, 2024). "CD34—associated with positive hormone receptors—is related to the appearance of the tumor in the vulvar region, which is characteristic of some of the mesenchymal tumors in this topography that arise from superficial, hormonally responsive stromal cells of the lower genital tract." (PMID 35252046, 2022). "Most investigators accept that SFT are mesenchymal tumors arise from dendritic stromal cells expressing the CD34 antigen, and can occur in any body part." (PMID 40710869, 2025). "Here, we reported ALK fusions involving related partner genes in two adult soft tissue tumors with S100 and CD34 co-expression, and conducted a literature review of mesenchymal tumors harboring ALK or other kinase fusions." (PMID 36387173, 2022). "ISFT is a rare mesenchymal tumor, which originates from CD34 positive dendritic mesenchymal cells and is named for its differentiation into fibroblasts and myofibroblasts." (PMID 36281132, 2022). "Endoscopic ultrasonography-guided fine-needle aspiration revealed CD34-positive spindle-shaped cells in the fibrous tissue, suggestive of a mesenchymal neoplasm." (PMID 35676716, 2022). "CD34 is useful to distinguish CCS from Epithelioid neoplasms with SMARCB1 and SMARCA4 deficiency or Mesenchymal tumors with NTRK fusions which are positive for CD34." (PMID 33478436, 2021). "CD34 has been used as a conventional marker of SFT; however, some mesenchymal tumors histologically mimicking SFT also express CD34." (PMID 30168002, 2018). "A diagnosis of malignant mesenchymal tumor was excluded due to negativity for desmin, smooth muscle actin, caldesmon, CD34, CD10, and myoglobin." (PMID 27491291, 2016). "AMFs are characterized by the expression of vimentin, desmin and CD34, suggesting an undifferentiated mesenchymal tumor with preferential myofibroblastic differentiation." (PMID 24894537, 2014). "Cytokeratin positivity aids with differentiating PBL from poorly differentiated carcinomas, and GIST is a common mesenchymal tumor of the small intestine, which is usually characterized by CD34 and CD117 expression." (PMID 25364423, 2014). "CD34 also stains a wide variety of mesenchymal tumours but the focal nature of expression in this case would reduce any diagnostic significance." (PMID 24060090, 2013). "In conclusion, this study expands the morphological and genetic landscape of tumors with S100 and CD34 co-expression harboring kinase fusions, and suggests that kinase fusion-positive mesenchymal neoplasms are becoming an enlarging entity with a variety of morphological patterns." (PMID 36387173, 2022). "Positive findings of CD34 and vimentin only indicate a mesenchymal tumor." (PMID 27044420, 2016). "CD34 expression is also primarily observed in mesenchymal tumours." (PMID 24416158, 2014). "Among the vascular markers, CD34 and ERG are the least specific for endothelial cells; the former is expressed in many mesenchymal tumors and the latter is also found in epithelioid sarcomas and prostatic adenocarcinomas." (PMID 38374236, 2025). "Superficial CD34-positive fibroblastic tumor (SCPFT) is a recently identified, infrequent, low-grade mesenchymal neoplasm, first identified in 2014." (PMID 38021590, 2023). "GISTs are defined as pleomorphic mesenchymal tumors of the GI tract composed of spindle cells, epithelioid cells, or a combination of both, that express the c-KIT protein and, in most cases, CD34, as demonstrated by immunohistochemical staining." (PMID 25037940, 2014).
mesenchymal tumors (continued). "Positive immunoreactivity for CD34 and CD99 is characteristic of SFT, and highly valuable in differentiating from other mesenchymal tumors." (PMID 21970525, 2011). "More recently, ALK-rearranged mesenchymal tumors that are not IMTs or EFHs, characterized by S100 and CD34 coexpression, have been reported in a few small series and isolated case reports." (PMID 41672777, 2026). "Superficial biopsy and boring biopsy showed unspecific granulation tissues, and immunostaining revealed that the mesenchymal tumor was negative for CD34, c-kit, desmin, and S100 protein." (PMID 32428827, 2020). "Because SFT is a mesenchymal tumor, immunohistochemical staining is positive for CD34 and vimentin, and negative for mesothelial cell-derived cytokeratin and epithelial membrane antigen." (PMID 33188464, 2020). "GISTs are defined as pleomorphic mesenchymal tumors of the gastrointestinal tract composed of spindle cells, epithelioid cells, or a combination of both that express the KIT protein (CD 117) and in most cases CD34 on immunohistochemistry." (PMID 23243532, 2012). "Lack of CD34 and panTRK preclude an NTRK-rearranged mesenchymal tumor." (PMID 40705064, 2025).
spindle cell tumors (48 papers, 2006 to 2026). "In summary, we report two cases of S100 and CD34 positive polypoid spindle cell tumors of the uterine cervix harboring EGFR mutation which we believe represents a hitherto unrecognized variant of “NTRK-rearranged spindle cell neoplasms” of the uterus." (PMID 39387892, 2024). "While often less histopathologically subtle, DFSP can be identified by CD34 positivity and factor XIIIa negativity, distinguishing it from dermatofibromas and other spindle cell tumors." (PMID 41551622, 2026). "Immunohistochemically, NF typically shows strong positivity for SMA and vimentin, with negativity for markers such as S-100 protein, desmin, and CD34, which helps differentiate NF from malignant spindle cell neoplasms, such as sarcomatous lesions." (PMID 41585341, 2026). "Histopathological evaluation demonstrated a high-grade spindle cell tumor, initially interpreted as fibrosarcoma, showing diffuse vimentin positivity, a high Ki-67 proliferation index (35%-40%), and CD34 negativity." (PMID 41867924, 2026). "Unfortunately, CD34 is expressed in several spindle cell neoplasms, including neural tumors and dermatofibrosarcoma protuberans, hence, is not totally specific to SFTs." (PMID 40709355, 2025). "The specimen from the first surgery at our hospital contained an S100+, CD34+ mucinous spindle cell tumor." (PMID 40777560, 2025). "A 3 mm punch biopsy was performed, with pathology showing a CD34-positive spindle cell neoplasm extending to biopsy margins, consistent with DFSP." (PMID 41466943, 2025). "Punch biopsy revealed a CD34-positive spindle cell neoplasm, and fluorescence in situ hybridization confirmed COL1A1 rearrangement, consistent with DFSP." (PMID 41466943, 2025). "Histopathologically, the presence of an atypical myxoid spindle cell neoplasm with CD34 positivity further complicated the diagnosis." (PMID 39727618, 2024). "Histopathological analysis revealed a malignant spindle cell tumor, which was confirmed by a CD34 immunohistology stain." (PMID 39055444, 2024). "Histopathological examination revealed an atypical myxoid spindle cell neoplasm with CD34 positivity and an overlying mildly atypical compound melanocytic nevus." (PMID 39727618, 2024). "This case underscores the importance of considering SCL in the differential diagnosis of CD34-positive spindle cell tumors, even when the clinical and histological presentation deviates from the classic description." (PMID 39727618, 2024). "Further evaluation confirmed the presence of a spindle-cell neoplasm, which was mildly cellular and showed positive expression of CD34 and CD117 on immunohistochemistry, consistent with the diagnosis of GIST of the rectum." (PMID 37519537, 2023). "Histopathology revealed spindle cell tumor embedded in myxohyaline stroma along with hyalinized vascular channels demonstrating IHC positivity for CD34 and STAT6." (PMID 37533000, 2023). "Recently, a novel group of CD34 and S100 co-expression spindle cell tumors with distinctive stromal and perivascular hyalinization harboring recurrent gene fusions involving RET, RAF1, BRAF, and NTRK1/2 gene has been identified." (PMID 36229858, 2022). "A case study describing a spindle cell neoplasm with myxoid features, low-grade morphology, and CD34 and partly S100 protein immunohistochemical positivity, had a rather aggressive course." (PMID 33803146, 2021). "In 2016, a CD34-positive spindle cell neoplasm with an interesting, recurrent genetic anomaly was described: LPF-like neural tumor (LPF-NT), which was initially associated with NTRK1 gene fusions." (PMID 34449590, 2021). "There has been particular interest in CD34-positive spindle cell neoplasms, in view of their importance as a differential diagnosis for dermatofibrosarcoma protuberans (DFSP)." (PMID 34449590, 2021). "Two cases (LFLNT and low-grade spindle cell lung tumor) showed at least focal S100, and CD34 staining, and one case (high-grade spindle cell tumor) was only focally positive for CD34." (PMID 32860002, 2021).
spindle cell tumors (continued). "Different growth patterns of NTRK fused spindle cell tumors have been analyzed in the literature, while researchers have often focused on the role of CD34 and S100 in these cases." (PMID 33803146, 2021). "Mammary-type myofibroblastoma and spindle cell lipoma are benign, spindle cell neoplasms that show immunoreactivity with CD34." (PMID 30567070, 2018). "CD34 positivity distinguishes SFT from other spindle-cell tumors, and it is necessary to combine other markers for differential diagnosis." (PMID 21443810, 2011). "Correct interpretation of unique pathological findings and CD34 immunoreactivity plays a significant role in differentiating SFT from other spindle-cell neoplasms of the liver." (PMID 21443810, 2011). "In latter studies, the same investigators postulated that the "vimentin+/CD34+ cell" is the precursor cell of all benign spindle cell neoplasm." (PMID 16859566, 2006). "Histopathology showed a monomorphic spindle-cell infiltrate without atypia; immunohistochemistry (IHC) confirmed a CD34-positive, S100-negative spindle-cell neoplasm consistent with a myxoid variant of dermatofibrosarcoma protuberans." (PMID 41923966, 2026). "The resected tumor at that time manifested S100+, CD34+ mucinous spindle cell tumor." (PMID 40777560, 2025). "Other PK-related neoplasms in the differential diagnoses are the plaque-like stage of dermatofibrosarcoma protuberans (DFSP) and the ALK-rearranged CD34-positive spindle cell neoplasm/medallion-like dendrocyte hamartoma/plaque-like CD34-positive dermal fibroma." (PMID 40387903, 2025). "Spindle cell lipoma (SCL), dermatofibrosarcoma protuberans (DFSP), and solitary fibrous tumors (SFTs) are cutaneous CD34+ spindle cell tumors that may exhibit histopathologic and immunophenotypic overlap." (PMID 39727618, 2024). "These tumors are generally positive for CD34, STAT6, and other markers that help differentiate them from other spindle cell neoplasms." (PMID 40861561, 2025). "The immunohistochemical profile showed CD34 positivity with S100 and SOX10 negativity, which is typical for DFSP and helps differentiate it from other spindle cell neoplasms such as nerve sheath tumors." (PMID 41466943, 2025). "As previously stated, immunohistochemistry findings confirmed the recurrent tumor as a spindle cell neoplasm, with immunopositivity for CD31 (80-90%), CD34 (>90%), ERG (5-10%), and STAT6 (>90%)." (PMID 40861561, 2025). "Histologically, they exhibit a staghorn vascular pattern and express markers including CD34 and STAT6, helping to distinguish them from other spindle cell tumors." (PMID 41140989, 2025). "Immunohistochemistry confirmed the recurrent tumor as a spindle cell neoplasm, with immunopositivity for CD31 (80-90%), CD34 (>90%), ERG (5-10%), and STAT6 (>90%)." (PMID 40861561, 2025). "A spindle cell neoplasm emerging from a deeper anatomical area, such as an intraosseous vertebra, with EML4–ALK23 fusion and immunoreactivity for CD34 and S100 has also been reported." (PMID 39202049, 2024). "Immunohistochemistry frequently identifies SFT through positive staining for Vimentin, CD34, Bcl-2, and CD99, with CD34 serving as a critical marker to differentiate SFT from other spindle cell tumors." (PMID 39416460, 2024). "Immunohistochemical staining is also critical, with HPCs typically showing positivity for markers such as CD34, vimentin, CD99, and Bcl-2 and negativity for S100, which helps differentiate it from other spindle cell tumours." (PMID 39371697, 2024). "Cell surface protein markers CD31 and CD34, are helpful to differentiate ALM from other spindle cell tumor." (PMID 28877751, 2017). "An endoscopic biopsy of the gastric lesion revealed a spindle cell neoplasm which was strongly and diffusely immunoreactive for CD117, CD34, and DOG1." (PMID 25694839, 2015).
spindle cell tumors (continued). "CD34 immunoreactivity was consistently found in SFT and this marker facilitates histopathological differentiation of this lesion from other recognized spindle cell tumors of the orbit." (PMID 19384025, 2009). "Splenectomy revealed a solitary spindle cell tumor composed of bland smooth muscle fibers, diffusely positive for desmin and smooth muscle actin, and negative for C-Kit, CD34, and S100, confirming the diagnosis of splenic leiomyoma." (PMID 41209908, 2025). "In conclusion, we describe a rare case of CD34-negative, S100-positive spindle cell tumor with MYH10-RET fusion." (PMID 40873555, 2025). "This diagnostic profile is consistent with previous reviews, confirming the reliability of strong CD34 expression, low proliferative index, and absence of cytologic atypia as key features distinguishing spindle cell lipoma from other spindle cell neoplasms." (PMID 41283482, 2025). "Upon total resection, pathology showed a spindle-cell tumor positive for desmin but negative for CD34." (PMID 35509779, 2022). "ALK rearrangements have rarely been reported in S100- and CD34-co-expressing soft tissue neoplasms with lipofibromatosis-like neural tumor (LPFNT) pattern or stromal and perivascular hyalinization, mimicking NTRK-rearranged spindle cell tumors." (PMID 36387173, 2022). "While more than 90% of SFTs are CD34 positive, it is not specific because of its shared expression in many spindle cell tumours." (PMID 32566457, 2020). "Importantly, these tumors are negative for markers such as SMA, Desmin, EMA, Melan-A, and CD34, which aids in ruling out other spindle cell neoplasms." (PMID 41199828, 2025). "Notably, staining for c-kit and CD34 is negative, aiding in differentiation from other spindle cell tumors." (PMID 39835056, 2024). "These markers are, however, insufficient for distinguishing IMTs from other spindle cell tumors, but the combination with known negative IHC stains like CD117, CD34, and S100 confers a higher degree of certainty." (PMID 40390744, 2025). "CT-guided core biopsy was positive for high-grade spindle cell neoplasm (positive for smooth muscle actin, desmin, S100, and CD31; negative for CD34, PAX8, and beta-catenin) and verified by two independent pathologists." (PMID 30558620, 2018). "CT-guided core biopsy was positive for high-grade spindle cell neoplasm (positive for smooth muscle actin, desmin, S100, and CD31; negative for CD34, PAX8, and beta-catenin)." (PMID 30558620, 2018). "In summary, spindle cell tumors with a fibrosarcoma-, LPF-, myopericytoma/hemangiopericytoma-like or myxoid morphological pattern, positive for CD34 and/or S100 protein, but without a known driver oncogenic alteration, meet the suggested criteria for NTRK fusion testing." (PMID 33803146, 2021).
lung cancer (47 papers, 2002 to 2025). A malignant neoplasm involving the lung. "Previous studies have reported that Fibrocyte_CD34 promotes tumor growth and enhances angiogenesis within the cancer niche during lung cancer progression." (PMID 40725006, 2025). "First, CD34 positive microvessels in lung cancer tumor tissues as a differentiated microvessels tpye, which was more likely to display intratumoral mature blood vessels and peritumoral normal blood vessels." (PMID 39906069, 2025). "Based on the BioGPS database to assess the mRNA levels of 7 hub targets, the hub targets had elevated mRNA levels in lung cancer-related organs, including lung, SmoothMuscle, Cd34+ cells, cd33+ cells and Cd56+ cells." (PMID 39450260, 2024). "Flow cytometric analysis of PBMC from 18 patients with lung cancer on samples collected immediately before the first and the second treatment was performed to study Lin-CD34+DNAM-1bright CXCR4+ precursors." (PMID 38390333, 2024). "Nevertheless, lung cancer tumor tissues possess both differentiated (CD34 +) and undifferentiated (CD31 + /CD34-) microvessels." (PMID 38834833, 2024). "A recent study demonstrated that CAFs expressed high levels of PI16 and CD34 localized to the blood vessel adventitia in lung cancer." (PMID 39334513, 2024). "The observed increase in CD34+DNAM-1brightCXCR4+ cells in PBMC in patients with lung cancer following CT/IT has characteristics of a standard stereotyped defense reaction to inflammatory stimuli." (PMID 38390333, 2024). "CD34 has also been utilized as a biomarker to assess angiogenesis in multiple malignancies, such as cervical cancer, gastric cancer, lung cancer, and oral squamous cell carcinoma." (PMID 37241170, 2023). "Solid tumor CSCs (CD44+CD24−/lowLineage− cells) have been found in breast, ovarian, prostate, colon, pancreatic, liver, and lung cancers, suggesting that CD34+ and CD44+ are typical CSC markers." (PMID 34671679, 2021). "Antitumor efficacy was analyzed in HCC-827 lung cancer xenografts in humanized CD34+ mice at three dosage levels: 20, 80, and 200 mg/kg." (PMID 34456733, 2021). "Conversely, seven of the downregulated hub genes (TLR4, PECAM1, SELP, CXCL12, VWF, KDR, and CD34) showed both low expression and good prognosis in lung cancer patients (p < 0.05)." (PMID 33627711, 2021). "The correlations between CTP parameters with MVD and VEGF were analysed in 36 lung cancer patients who had extra sections be used for immunohistochemistry staining of CD34 and VEGF." (PMID 34717573, 2021). "Using an Hu-CD34+ HSC mouse model loaded with lung cancer PDX, researchers discovered high immune cell infiltration in the tumor." (PMID 33996603, 2021). "The positive rate of CD34 staining in 30 human lung cancer tissue samples was 83.3%, indicating that angiogenesis is common in lung cancer." (PMID 31186629, 2019). "We found 45 and 343 altered microRNAs for SP+ lung cancer stem cells and CD34+SCA1+ bone marrow hematopoietic stem cells, respectively." (PMID 28977934, 2017). "For example, a negative correlation between SD and MPP, and angiogenic burden (measured by antibodies to CD34) has been demonstrated in NSCLC lung cancer." (PMID 26867730, 2016). "Intratumoral MVD was quantified by counting CD34-positive endothelial cells in the same series of lung cancer tissues, and the staining intensity of MVD ranged broadly from 7 to 86 microvessels/200× magnification fields." (PMID 26791086, 2016). "Intratumoral MVD was quantified by counting CD34-positive endothelial cells in the same series of lung cancer tissues, and the average number of microvessels in ten fields was counted as a measure of MVD for each sample." (PMID 25162518, 2014). "An elevated number of endothelial progenitor cells (CD133+CD34+VEGFR2+) in patients with lung cancer have been previously reported, which was shown to correlate with disease stage and clinical behavior." (PMID 23959111, 2014).